FAM217A (family with sequence similarity 217 member A)
Synonyms: C6orf146; MGC43581
Tractability: PROTAC: ubiquitination databases record sites on it.
Gene: Protein-coding gene on chromosome 6 (4,049,434 to 4,087,344, reverse strand). Ensembl gene ENSG00000145975.
Gene Ontology:
Molecular function: protein binding
Genetic constraint (gnomAD): Loss-of-function variants: 7 observed, 11.88 expected, observed/expected ratio (o/e) 0.59, 90% interval 0.33 to 1.11. The synonymous counts are far from expectation, so gnomAD's model fits this gene poorly and the ratio says little. Missense variants: 545 observed, 586.76 expected, observed/expected ratio (o/e) 0.93, 90% interval 0.87 to 1. Synonymous variants: 161 observed, 212.31 expected, observed/expected ratio (o/e) 0.76, 90% interval 0.67 to 0.86.
Homologues: Orthologues: chimpanzee FAM217A (99% identical), macaque FAM217A (88% identical), mouse Fam217a (61% identical), rabbit FAM217A (61% identical), rat Fam217a (61% identical), zebrafish fam217bb (11% identical), zebrafish fam217ba (7% identical). Paralogues in human: FAM217B (13% identical).
Diseases named in the same sentence as FAM217A in open-access papers:
FAM217A is named in the same sentence as 1 disease in open-access papers, as found by Europe PMC text mining. Sharing a sentence is not in itself a finding about the gene and the disease.
FAM217A shares sentences with these, for which no sentence is quoted: cancer (1 paper).